CASR (calcium sensing receptor)
Diseases named in the same sentence as CASR in open-access papers (continued):
Sharing a sentence is not in itself a finding about the gene and the disease.
chronic kidney disease (22 papers, 2008 to 2025). Impairment of the renal function secondary to chronic kidney damage persisting for three or more months. "In 2HPT of chronic kidney disease, parathyroid gland hyperplasia, especially in its nodular form, is associated with reduced expression of CaSR and VDR, determining medical therapy resistance." (PMID 23232027, 2012). "CaSR plays a critical role in regulating mineral metabolism, and its dysregulation is closely linked with vascular calcification, particularly in patients with chronic kidney disease (CKD)." (PMID 41208959, 2025). "Administration of cinacalcet, an alternative ligand of calcium-sensing receptor decreasing the production of parathyroid hormone and thereby lowering serum calcium and phosphate, to the patients with chronic kidney disease reduced the risk of major adverse cardiovascular events." (PMID 36499266, 2022). "We hypothesized that CASR rs7652589 variants may also influence CaSR in end stage renal disease (ESRD)." (PMID 27739473, 2016). "We hypothesized that CASR rs7652589 variants may also influence CaSR in chronic kidney disease, particularly in ESRD." (PMID 27739473, 2016). "Cinacalcet, an oral calciomimetic that decrease PTH secretion binding calcium sensing receptor, has been used with success mainly in chronic renal failure patients." (PMID 36998475, 2023). "Analysis of epigastric arteries, taken from chronic kidney disease patients, showed that a decrease in CaSR expression was accompanied by progressive calcification of VSMC areas." (PMID 23340319, 2013). "In the GPCR field, cinacalcet, an allosteric enhancer of the calcium-sensing receptor (CaR), has recently been approved for the treatment of secondary hyperparathyroidism in dialysis patients suffering from chronic kidney disease." (PMID 19077268, 2008). "The CaSR has a pivotal role in maintaining Ca2+ homeostasis in the kidneys, and the activation of the CaSR might protect against kidney injury or chronic kidney disease (CKD)." (PMID 36231037, 2022). "CaSR may also be involved in another dangerous pathology affecting the cardiovascular system: the vascular calcification, a common complication of chronic kidney disease (CKD)." (PMID 31717830, 2019). "One hypothesis is that serum phosphate may regulate the expression of the calcium-sensing receptor by the parathyroid glands, as evidenced by the reduced presence of the calcium-sensing receptor in the parathyroid glands of patients with chronic renal failure." (PMID 29295646, 2018). "SHPT is a common disorder that occurs in chronic kidney disease (CKD), characterized by significantly reduced expressions of CaSR and vitamin D receptor (VDR), which largely contributes to death and cardiovascular events in CKD patients." (PMID 36755240, 2023). "Pathological examinations of parathyroid glands in patients with chronic CKD and/or end-stage renal diseases (ESRD) have revealed transformation from diffused to nodular hyperplasia, accompanied by the decrease in CaSR and VDR levels." (PMID 36755240, 2023). "In addition, a substantial role of the CaSR in maintaining normal blood pressure and cardiovascular functions is supported by studies on the effect of so-called calcimimetics, i.e., synthetic allosteric activators of the CaSR, in various animal models and patients with chronic kidney disease." (PMID 23340319, 2013).
osteoporosis (22 papers, 2007 to 2025). A condition of reduced bone mass, with decreased cortical thickness and a decrease in the number and size of the trabeculae of cancellous bone (but normal chemical composition), resulting in increased fracture incidence. "With regard to osteoporosis, osteoclasts and osteoblasts have CaSR, and osteoporosis is associated with changes in glutathione-associated enzymes." (PMID 35054903, 2022). "Genetic polymorphisms in the CaSR, a gene that encodes for the calcium sensing receptor and mainly regulates calcium homeostasis, has been associated with determining the prevalence of osteoporosis in aging males." (PMID 33805567, 2021). "In conclusion, CaSR enhances OB differentiation, likely via Homer1-mediated regulation of AKT signaling, suggesting CaSR as a potential therapeutic target for osteoporosis." (PMID 40059879, 2025). "As more than 50% of patients with FHH3 exhibit decreased bone density, CaSR signals play important roles in bone formation, and patients are likely to develop osteoporosis or osteomalacia." (PMID 39949382, 2025). "Due to its ability to regulate PTH secretion, CaSR has therapeutic potential for the treatment of disorders of calcium homeostasis and osteoporosis." (PMID 40510119, 2025). "CaSR and PTH1R are pivotal for calcium homeostasis, with CaSR alleles associating with BMD and osteoporosis risk, and PTH1R agonists (e.g., teriparatide) serving as therapeutic agents for osteoporosis by enhancing bone formation 32-35." (PMID 40860192, 2025). "Further studies are necessary to determine how pathological conditions involving monocytes/macrophages, such as rheumatoid arthritis, atherosclerosis or osteoporosis, modify CaSR expression." (PMID 24098349, 2013). "Recent studies do indeed indicate the possibility of treating bone diseases such as osteoporosis by CaSR allosteric modulators (calcimimetics and calcilytics)." (PMID 24040082, 2013). "CASR has been previously considered as a candidate gene for osteoporosis and coronary heart disease as well as increased total and cardiovascular mortality." (PMID 20661308, 2010). "A post-oophorectomy osteoporosis model was established in Sprague-Dawley rats, validated through micro-computed tomography, hematoxylin-eosin staining, and biomechanical testing to assess in vivo changes in CaSR expression." (PMID 40059879, 2025). "In addition, both the calcium-sensing receptor (CASR) and the interleukin 6 (IL-6) are important candidate genes for osteoporosis as well as in bone and mineral metabolism." (PMID 18036257, 2007). "Several CaSR-negative allosteric modulators have undergone clinical trials for osteoporosis, although all failed to stimulate new bone formation." (PMID 40510119, 2025). "Aside from possible roles in renal disease, changes in glutathionergics and CaSR function may also have roles pathology in HIV-AIDs, osteoporosis, pulmonary hypertension, and neurodegenerative diseases." (PMID 35054903, 2022). "A recent meta-analysis focusing on effects of candidate genes on osteoporosis also reports negative results for CASR." (PMID 20661308, 2010). "The mechanism of the Sr2+ anti-osteoporosis action appears to be different from those: it does not fully substitute for the native Ca2+ in CaSR but rather binds and activates the receptor as it closely mimics the basic physico-chemical and structural features of the native agonist." (PMID 34827574, 2021).
Hypertension (21 papers, 2012 to 2025). The presence of chronic increased pressure in the systemic arterial system. "In pathological conditions such as hypertension and atherosclerosis, CaSR activation has been linked to increased VSMCs proliferation and calcification, contributing to vascular stiffness and plaque development." (PMID 41208959, 2025). "Several cardiovascular conditions, including hypertension, atherosclerosis, cardiac hypertrophy, myocardial infarction (MI), and vascular calcification, have been associated with altered CaSR expression or signaling." (PMID 41208959, 2025). "The results showed that a decrease in CaSR in hypertensive rats causes further development of hypertension and cardiac damage." (PMID 38715976, 2024). "The CaSR is also implicated in the pathophysiology of cardiovascular diseases, such as myocardial infarction (MI), heart failure, hypertension, atherosclerosis, vascular calcification, and ischemia/reperfusion (I/R)-injury." (PMID 36467702, 2022). "The normal expression of CaSR thereby functions as a protective shield against hypertension and its associated cardiac pathologies." (PMID 33804544, 2021). "Together, these findings indicate that CaSR is associated with the synthesis and deposition of collagen and that it participates in aortic fibrosis in hypertension." (PMID 30906225, 2019). "Further studies using CaSR agonist- and antagonist-based strategies are needed in order to elucidate the role of the CaSR in the pathogenesis of hypertension, and to understand the underlying mechanisms such as the G-PLC-IP3-Ca2+ signal transduction pathway." (PMID 27391973, 2016). "Studies have shown that the resistance arteries of diabetic rats exhibit lower levels of CaSR expression, which may disrupt Ca2+ homeostasis and contribute to the development of hypertension and other vascular dysfunctions associated with DM2." (PMID 40556956, 2025). "However, little is known about the role of the CaSR in phenotypic modulation of VSMCs in hypertension, and the underlying mechanisms are poorly understood." (PMID 27391973, 2016). "This suggests that CaSR not only participates in myocardial injury through the ER pathway, but also plays a significant role in cardiomyocytes apoptosis induced by hypertension by regulating mitochondrial dynamics." (PMID 41208959, 2025). "Consequently, the CaSR has been implicated in regulating systemic and pulmonary blood pressure and calcimimetics and calcilytics are potential therapeutic targets for cardiovascular diseases, such as hypertension, pulmonary artery hypertension, and atherosclerosis." (PMID 39912052, 2025). "Emerging evidence suggests that altered CaSR expression contributes to the development and progression of cardiovascular conditions such as hypertension, atherosclerosis, cardiac hypertrophy, MI and vascular calcification." (PMID 41208959, 2025). "Studies have shown that CaSR in VSMCs plays a very important role in maintaining blood pressure levels within physiological limits, thus reducing hypertension." (PMID 41208959, 2025). "This study provides convincing evidence that CaSR can attenuate hypertension-mediated myocardial remodeling." (PMID 38715976, 2024). "We therefore found a new mechanism of cardioprotective effect of CaSR, one which also offers a novel theoretical basis for the therapy of hypertension-induced myocardial remodeling." (PMID 38715976, 2024). "In a rat model of hypertension, in particular in vSMCs, the CaSR has been found to promote the release of pro-inflammatory cytokines through the NLRP3 inflammasome." (PMID 36467702, 2022). "The results in SHRs suggested that sodium ferulate protected against hypertension-induced cardiac hypertrophy by inhibiting the CaSR-mediated CaN-NFAT-3 signaling pathway." (PMID 36231037, 2022).
Hypertension (continued). "Previous studies have demonstrated that the CaSR mediated the inflammation that influences the cardiovascular system, such as atherosclerosis, vascular calcification, myocardial infarction, hypertension, and obesity." (PMID 36231037, 2022). "A study conducted on rats with spontaneous hypertension indicated that CaSR is selectively activated in the myocardium triggering reverse cardiac remodeling." (PMID 33804544, 2021). "In rats with spontaneous hypertension, AngII also activates CaSR, as well as NLRP3 inflammasome in vSMCs." (PMID 33804544, 2021). "The calcium‐sensing receptor (CaSR) is involved in the pathophysiology of many cardiovascular diseases, including myocardial infarction (MI) and hypertension." (PMID 33043596, 2020). "In this study, we tested the role and mechanism of calcium-sensing receptor (CaSR) in NLRP3 inflammasome activation during hypertension." (PMID 30906225, 2019). "And NLRP3 inflammasome was involved with CaSR-mediated fibrosis during hypertension, which led to IL-1β and IL-18 release." (PMID 30906225, 2019). "To determine the role of CaSR in hypertension, we treated SHRs with Calhex 231 and found that the increased levels of blood pressure in SHRs were attenuated." (PMID 30906225, 2019). "The purpose of this study was to investigate the role and potential mechanisms of CaSR in aortic remodeling during hypertension." (PMID 30906225, 2019). "In the human groups, the CaSR content in the plasma samples from the hypertension group was significantly lower than in the normal group (P < 0.05)." (PMID 27391973, 2016). "In order to investigate the mechanism by which the CaSR affects vascular cell proliferation and remodeling in hypertension, we focused on the roles of cAMP and the RAS." (PMID 27391973, 2016). "These interventions not only reduce proteinuria and preserve the GFR but also limit immune infiltration and fibrosis, supporting a pathophysiological role for the CaSR at the intersection of oxidative, immune, and tubular injury in hypertension-induced nephropathy." (PMID 40806733, 2025). "In SHR models, CaSR downregulation is associated with endothelial dysfunction, increased vasoconstriction, and activation of the RAAS, creating a feedback loop that results in vascular stiffness, hypertension, and renal hypoperfusion." (PMID 40806733, 2025). "In these two studies, they applied only one modulator of the CaSR as treatment, but it is interesting that both the activation and inhibition of the CaSR could protect the myocardia against hypertension." (PMID 36231037, 2022). "Although these studies had not identified the downstream effectors of the CaSR-mediated CaN-NFAT-3 signaling pathway, they confirmed that the CaSR could regulate the ER–nucleus communication in hypertension-induced cardiac hypertrophy." (PMID 36231037, 2022). "The CaSR might mediate the Ca2+ transfer from the ER to mitochondria and regulate the mitochondrial dynamics, which contribute to cardiac hypertrophy and hypertension." (PMID 36231037, 2022). "Our findings provide new insights into the pathogenesis of this complex disease, and suggest that the vascular CaSR pathway may be a therapeutic target in the management of hypertension." (PMID 27391973, 2016). "While low calcium intake from diet can thus be linked to the development of osteoporosis and of various malignancies, involvement of the CaSR in the pathogenesis of other calcium insufficiency-related chronic diseases, such as hypertension and cardiovascular disease, is not yet fully understood." (PMID 23340319, 2013). "Previous studies revealed that the CaSR could be a potential therapeutic target for hypertension." (PMID 36231037, 2022). "Therefore, we hypothesized that a decrease in the expression of CaSR may contribute to hypertension, possibly though activation of the RAS." (PMID 27391973, 2016).
Hypertension (continued). "Accumulating evidence suggests that the CaSR is functionally expressed in the vasculature and may play a major role in the pathogenesis of arterial calcification, which accompanies the development of atherosclerosis, arteriosclerosis and hypertension." (PMID 26436544, 2015). "Consequently, impairment of Ca2+/CaSR signaling may contribute to inadequate bone formation, tumor progression, hypertension, vascular calcification and, probably, cardiovascular disease." (PMID 23340319, 2013). "As a negative allosteric modulator of the CaSR, Calhex231 decreased the heart-to-body weight ratio and the protein levels of the CaSR and attenuated myocardial apoptosis during hypertension." (PMID 36231037, 2022). "In this model, it is speculated that CaSR activation in VSMCs increases cytosolic [Ca2+]i, which stimulates NLRP3 inflammasome activation and leads to IL-1β and IL-18 maturation during hypertensive aortic fibrosis." (PMID 30906225, 2019). "Together, these findings suggest that CaSR contributed to collagen synthesis by activating MMP activity in VSMCs treated with Ang II and may be involved in aortic remodeling in hypertension." (PMID 30906225, 2019). "However, the role of CaSR-mediated NLRP3 inflammasome activation in hypertension has not yet been investigated." (PMID 38715976, 2024). "We hypothesize that CaSR expression and/or functional impairment weakens the inhibition of adenylate cyclase (AC) and increases cAMP formation and renin release, resulting in activation of the RAS, which induces VSMC proliferation and remodeling, thereby promoting the development of hypertension." (PMID 27391973, 2016).
diabetes (20 papers, 2010 to 2024). "Thus, our study focus on the role of CaSR in HG-induced EndMT, which might underlie the mechanism cardiovascular diseases in diabetes." (PMID 33519531, 2020). "Ca2+-sensing receptor (CaSR) existed in endothelial and smooth muscle cells and the dysregulated CaSR function and expression may predispose to the macrovascular late complications associated with diabetes." (PMID 32751309, 2020). "Although the report was directed towards the management of diabetes and intestinal inflammation, the CaSR mRNA, which showed suppression in one study and upregulation in the other, also plays a vital role in the CaSR axis of bone homeostasis." (PMID 35955603, 2022). "Among the 106 patients included, 45 were women (42.5%), 38 had diabetes (type 2 diabetes in all cases) (35.8%), 61 had been prescribed CaSR agonist (57.5%), and 97 had been prescribed VDRA (91.5%)." (PMID 34372813, 2021). "Our data in mesenteric arterioles observed that CaSR expression was depressed in diabetes suggesting an impairment of Ca2+-mediated relaxation in diabetic vessels." (PMID 32751309, 2020). "Erectile dysfunction (ED) is one of the significant complications of diabetes mellitus (DM), and CASR plays an important role in cellular antiapoptosis and NO production in the vascular endothelium by activating PKC." (PMID 31922200, 2020). "Cinacalcet reduced albuminuria without influencing either blood glucose or Ca2+ concentration and ameliorated diabetes-induced renal damage, which were related to the increased expression of calcium-sensing receptor and the phosphorylation of CaMKKβ-LKB1." (PMID 29449563, 2018). "Our study has revealed that the A986S CASR SNP is a predictor of serum glucose concentrations independently of BMI and the presence of diabetes mellitus." (PMID 25786244, 2015). "After the model of diabetes mellitus was established, rats were sacrificed and ventricular tissues were prepared to assess the CaSR protein expression after two months of STZ administration." (PMID 23717692, 2013). "The present study was designed to investigate the relationship between CaSR activation and diabetes-induced cardiac injury." (PMID 23717692, 2013). "During metabolic stress like diabetes, the impaired CaSR activity may contribute to the macrovascular late complications." (PMID 32751309, 2020). "Thus, based on the results obtained, we proposed that CaSR expression was different in type 1 and type 2 diabetes mellitus, but more detailed studies should be done." (PMID 23717692, 2013). "However, the expression and function of CaSR in diabetes-induced cardiac injury are poorly understood." (PMID 23717692, 2013). "Therefore, the aim of the present study was to evaluate the involvement of CaSR in diabetes-induced cardiac injury and to explore possible mechanism." (PMID 23717692, 2013). "However, the effect of diabetes on CaSR function and expression in regulating vascular reactivity is unknown." (PMID 32751309, 2020). "The twofold higher prevalence of diabetic mellitus and the significant difference in terms of fasting glucose concentrations between control subjects and RA patients may therefore constitute a possible confounder for interpretation of CaSR protein levels." (PMID 25134967, 2014). "However, very little is known about the role of CaSR in diabetes-induced cardiac apoptosis as yet." (PMID 23717692, 2013). "Therefore, we speculated that the CaSR could be directly or indirectly involved in diabetes-induced cardiac injury." (PMID 23717692, 2013). "We have also identified that several well-characterised GPCRs (CASR, GPRC5B, GPR119, F2RL1), which are either current drug targets or under evaluation as potential diabetes therapeutic targets, are highly expressed in both human and mouse islets." (PMID 28422162, 2017).